S100A8 (S100 calcium binding protein A8)
Diseases named in the same sentence as S100A8 in open-access papers (continued):
Sharing a sentence is not in itself a finding about the gene and the disease.
infection (continued). "The authors found multiple alarmins (HMGB1, IL-33, S100A8, and S100A9) in the joint capsule of the FS patient group in amounts consistent with an infection, while in the control group they found no significant increase of infection related markers." (PMID 34046418, 2021). "Candidalysin independent mechanisms of S100A8 and LL37 release may also exist, as we find the absence of candidalysin does not completely abrogate induction of either protein during infection." (PMID 32178483, 2020). "Additional analysis of several cytokines (Tnf-α, Il-6, IL-1β, and IFN-γ) and antimicrobial factors (Reg3γ, S100a8, and S100a9) found to increase during RIMD infection showed a similar trend, i.e., they were also strongly induced by infection with POR1 or POR2 but not POR3." (PMID 31848276, 2019). "IL-22-deficient mice were susceptible to C. albicans in the early but not late stages of infection, as indicated by signs of vaginal epithelial damage and inflammation, robust PMN recruitment, high S100a8 and S100a9 gene expression, calprotectin levels and fungal growth at 3 dpi." (PMID 23853597, 2013).
tumor (591 papers, 2006 to 2026). "The significant association of immune-related S100A8 expression with patient age and histologic grade supports its link to age-related immune dysregulation and tumor dedifferentiation." (PMID 41303754, 2025). "The S100 protein family has been implicated in tumorigenesis in various malignancies, with S100A8 emerging as a particularly important regulator of tumor–immune interactions." (PMID 41303754, 2025). "This study aimed to evaluate the expression patterns of S100A8 in both tumor and immune cells of EC and examine its association with clinicopathological features." (PMID 41303754, 2025). "In parallel, multiplex analyses and genomic profiling have revealed that expression levels of TGF-β pathway components (e.g., SMADs, TGFBRI/II, S100A8) are closely associated with clinical stage, survival, and tumor aggressiveness." (PMID 40806457, 2025). "S100A8 has been implicated in both tumor growth and chemotherapy sensitivity, and functional studies have shown that its downregulation increases apoptosis and enhances response to paclitaxel." (PMID 41303754, 2025). "These proteins also interact with the tumor immune microenvironment, with S100A8 and S100A9 being associated with immune infiltration and inflammatory pathways." (PMID 41303754, 2025). "Our retrospective study assessed liquid biopsies and tumor tissue analyses for two potential biomarkers: danger-associated molecular pattern (DAMP) S100A8/A9 and its source, neutrophils." (PMID 39700646, 2024). "Some members of this family, such as S100A4, S100A8/A9, S100P, and S100B, mediate the interaction between tumor and stromal cells, and thus, have been implicated in tumor progression, angiogenesis, and metastasis." (PMID 38499391, 2024). "The interaction with S100A8 can influence several aspects of tumor biology, which is associated with immunosuppression and TME remodeling through driving the polarization of macrophages toward an M2-like phenotype." (PMID 38361783, 2024). "Previous studies have reported that the overexpressed S100A8/S100A9 in tumor tissues is closely related to tumor‐associated inflammation, epithelial–mesenchymal transition, and metastasis, contributing to poor prognosis." (PMID 38962427, 2024). "While high levels of COPS3, DYHC1, and S100A8 were unfavorable for tumor recurrence, low amounts of A2M and Serpine 1 were associated with better DFS." (PMID 37174723, 2023). "We identified two clusters of tumor-associated neutrophils, both of which were substantially expressed in HM tissues, especially the S100A8+ neutrophils." (PMID 37612267, 2023). "The main factors associated with PMN-MDSCs tumor infiltration and especially with their immune suppression activity include S100A8/9 and iNOS expression." (PMID 37370739, 2023). "In HER2low TNBC group, the fate 1 branch was predominantly associated with module 2 genes (PTN, KRT15, S100A8, etc.)which suggested the tumor harbored the features of apoptosis, migration and metabolism." (PMID 36998014, 2023). "Remarkably, S100A8 is considered an independent prognostic factor for lower survival rates, and at high levels, it alters tumor-associated immune profiling, showing a lower proportion of M1 macrophages and dendritic cells." (PMID 37174723, 2023). "Higher proportions of S100A8 + tumor epithelial cells were significantly associated both with increased proliferation and with higher histopathological grade." (PMID 37450087, 2023). "A weak association between S100A8 staining in tumor epithelial cells and axillary lymph-node status at the time of diagnosis was observed (p = 0.08)." (PMID 37450087, 2023). "Cluster 0 cells showed minimal transcriptional overlap with above known tumor-associated myeloid cells types, except overexpressing inflammatory response genes S100a8/9 and myeloid differentiating gene Cebpb, and pathogen recognizing gene Cd14." (PMID 37055410, 2023).
tumor (continued). "This review comprehensively summarizes the biological functions of S100A8/A9 and its various receptors in tumor cells, in order to provide new insights and strategies targeting S100A8/A9 to promote novel diagnostic and therapeutic methods in cancers." (PMID 37701037, 2023). "We found that both S100A8 protein expression in tumor cells and, to a lesser extent, S100A8 CN increase, were associated with high tumor grade and increased proliferation." (PMID 37450087, 2023). "CCL3 and CXCL1 are pro-inflammatory cytokines and recruit tumor-killing cells, while S100A8/A9 is linked to metastasis." (PMID 37553342, 2023). "In line with earlier reports, accumulation of immunosuppressive M-MDSCs in tumor passage was further supported by the enhanced expression of S100A8 and S100A9, two calcium binding S100 proteins, associated specifically with M-MDSC." (PMID 38304256, 2023). "S100A8 expression is also associated with tumor stage in malignancies such as HNSC, KIRC, SKCM, TGCT, and THCA." (PMID 35646116, 2022). "The protein complex S100A8/S100A9 is an important promoter of tumor invasiveness and has been associated with poor prognosis." (PMID 33401528, 2021). "The data suggest a mechanistic connection between noradrenaline, causing MDSCs or neutrophils to release the protein S100A8/A9, eventually causing tumor cells to exit their dormancy and form new tumor lesions." (PMID 33494360, 2021). "We first analyzed the mRNA expression levels of damage-associated molecules (HMGB1, HSP60, HSP70, S100A8, IL-1A, IL-33) in 11 canine tumor cell lines." (PMID 33875721, 2021). "The homing of integrin αvβ5-expressing exosomes to fibronectin-rich liver microenvironments stimulates Kupffer cells to produce proinflammatory S100A8 and S100P implicated in facilitating tumour metastasis." (PMID 35006432, 2021). "On the other hand, high extracellular S100A8/A9 levels have cytotoxic effects by inducing cell death program or apoptosis in various tumor cells, independently of RAGE or Fas-associated protein with death domain (FADD)-dependent death receptors." (PMID 33567747, 2021). "The susceptibility to tumor colonization was restored by the human S100A8 (MRP8) promoter directing a functional Ncf1 expression to granulocytes." (PMID 34257370, 2021). "We also demonstrate interplay between tumor micro and macroenvironment and identified S100A8 as a potential marker with diagnostic and prognostic value in GBM." (PMID 30808902, 2019). "The local S100A8/A9-release correlated with the accumulation of tumour-associated CD11b+ cells and proved predictive of tumor development." (PMID 28744322, 2017). "In the tumor microenvironment, free extracellular S100A8/A9 is associated with tumor-associated inflammation and progression in certain types of cancer." (PMID 26883112, 2016). "As discussed in Section 2, PPARδ regulates the inflammatory Saa1/2/3 and S100a8/9 pathways, which in tumor-bearing mice are associated with MDSC expansion and metastasis." (PMID 28077942, 2016). "Secretion of S100a8 by primary tumours has also been implicated in the formation of the pre-metastatic niche in mouse lung." (PMID 25633981, 2015). "Elevated expression of MMP-3, Pthlh and S100a8 was confirmed in isolated primary tumour epithelial cells of the two metastatic variants, as was expression of S100a9, a binding partner for S100a8." (PMID 25633981, 2015). "MMP-3, S100a8, S100a9 and Pthlh transcripts were all upregulated significantly in isolated primary tumour cells of the metastatic variants in both pairs, reflecting the deregulation observed in whole tumours." (PMID 25633981, 2015). "In investigating tumor-stromal interactions, particular attention should be paid to the inflammatory proteins S100A8 and S100A9, which are encoded by genes clustered on chromosome 1q21." (PMID 24670043, 2014). "Further loss of S100A8/A9 expression in tissues would be expected to accelerate tumor growth and malignant transformation in HNSCC." (PMID 23874958, 2013).
tumor (continued). "At least 16 genes that encode members of the S100 family, including the gene for S100A8, are clustered on human chromosome 1q21, in a region that frequently experiences chromosomal rearrangement during tumor development." (PMID 20096140, 2010). "Therefore, this study employed TMAs to comprehensively assess S100A8 expression in both tumor and immune cells and to investigate its associations with clinicopathological parameters." (PMID 41303754, 2025). "Notably, the marked upregulation of S100A8/A9 not only serves as a hallmark of neutrophil infiltration and a pro-inflammatory tumor microenvironment, but is also closely linked to the activation of immune-related pathways." (PMID 41480141, 2025). "Moreover, tumor-associated macrophages (TAMs) and myeloid-derived suppressor cells (MDSCs) are recruited and polarized by S100A8/A9 and S100P, reinforcing an immunosuppressive milieu that limits cytotoxic T cell infiltration." (PMID 41404073, 2025). "By contrast, immune-related expression (i.e., IPS) significantly correlated with patients’ age and histological grade, indicating that S100A8 activity in the immune microenvironment may be linked to tumor differentiation and host immune responses." (PMID 41303754, 2025). "This confirmed that the loss of S100A8 helped Sec C to deprive tumor cells of stemness traits." (PMID 38607060, 2024). "Next, we asked whether this GDC-0339-induced reduction in day 5 tumor S100A8 and -A9 and serum S100A8/A9 levels is associated with changes in the abundance of select immune cell types in tumors, namely CD8 T cells, Tregs, and MDSCs." (PMID 38378783, 2024). "Notably, genes S100A1 and S100A8, which encode for the calprotectin complex, demonstrated a significant upregulation, with a threefold increase in expression observed in 80% of the tumor samples." (PMID 38979413, 2024). "Interestingly, HPV (+) OSCC tumor cells expressed the pathogen-associated pattern receptor, which, when activated, triggered S100A8 and NFκB activation and responses." (PMID 37174723, 2023). "Furthermore, the HPV (+) OSCC tumor cells expressed the pathogen-associated pattern receptor, which, when activated, promotes S100A8 and NFκB inflammatory responses." (PMID 37174723, 2023). "This is consistent with the reduced expression of many of the known genes that contribute to M-MDSC-suppressive function as identified in our scRNAseq dataset, including S100a8, S100a9, Ccl22 and Bcl2a1a which decreased in tumor M-MDSCs in ILC2-deficient settings." (PMID 35658010, 2022). "Moreover, S100A8 modulates tumor development and immunological responses in TME-associated macrophages." (PMID 35646116, 2022). "Interestingly, S100A8/A9 expression has also been linked to tumor development, invasion, or metastasis." (PMID 35783639, 2022). "Intriguingly, in these S100a8-cre-Il15fl/flPyMT mice, the loss of cancer-cell derived IL-15 resulted in reduced αβILTCK recruitment into the tumour tissue and impaired cancer immunosurveillance, with accelerated tumour growth in comparison to wild-type controls." (PMID 35768418, 2022). "Tumor-associated neutrophils have been shown to produce Bv8 and S100A8 in a mouse melanoma model." (PMID 35158807, 2022). "The protein complex S100A8/S100A9 has been associated with poor tumor prognosis." (PMID 33401528, 2021). "Inhibition of downstream regulator S100A8/9 may help to promote tumor eradication as increased expression has been associated with tumor growth and MDSC accumulation." (PMID 31953577, 2020). "However higher counts of peritumoral and intratumoral S100A8/A9 positive cells were associated with larger tumor size, higher grade, and the presence of metastasis (P < 0.05)." (PMID 25371673, 2014). "Furthermore, CD10High CSCs could recruit and reprogram tumor-associated neutrophils (TANs) in an immunosuppressive state by secreting S100A8/A9 in OSCC." (PMID 39897030, 2025).
tumor (continued). "In addition, we addressed the relationship between S100A8/A9 target genes and human cancer gene annotations from UniProt, Network of Cancer Genes, Tumor Suppressor Gene database, ONGene, and Tumor Associated Gene database." (PMID 33523865, 2021). "Likely released by infiltrating polymorphonuclear leukocytes, macrophages, and by epithelial cells, extracellular S100A8/A9 in the tumor microenvironment is associated with inflammation-induced tumor progression and may serve as a prognostic marker in some types of cancer." (PMID 26883112, 2016). "PDAC-associated S100A8 degradation may be governed by a regulatory mechanism restricting its function, but the release of peptides with their own biological activity might circumvent this phenomenon and modify tumor biology." (PMID 24670043, 2014). "S100A8/A9 can regulate multiple signaling pathways, including intracellular calcium, oxidative stress, and apoptosis in tumor cells." (PMID 41491331, 2026). "Previous studies have established that S100A8/A9 regulates cell metabolism in the tumor microenvironment, such as carbon metabolism, lipid metabolism, and ROS generation." (PMID 41513624, 2026). "ST analysis showed widespread NETs distribution in tumor tissues, with NETs-related markers S100A8, FUT4, LCN2, S100A9, and HSP3A exhibiting high expression across tissue regions." (PMID 41488283, 2026). "In EC, multiple S100 proteins, including S100A1, S100A2, S100A4, S100A8, and S100A9, have been implicated in tumor proliferation, invasion, epithelial–mesenchymal transition (EMT), and response to chemotherapy." (PMID 41303754, 2025). "The absence of an association between TI and IPS further emphasizes that the staining intensity in tumor cells alone is insufficient to capture the immunological dynamics of S100A8 expression." (PMID 41303754, 2025). "In contrast, S100A8 mRNA expression in tumor tissues is lower, possibly due to downregulation by tumor cells." (PMID 40963634, 2025). "Despite these findings, the clinical and prognostic significance of S100A8 in EC—particularly regarding its differential expression in tumor versus immune compartments—remains poorly understood." (PMID 41303754, 2025). "Oxidation of S100A8/A9 alters their dimerization status and inflammatory potential, functioning as a molecular switch between pro-tumor and anti-tumor states under oxidative stress conditions." (PMID 41404073, 2025). "Among these, MMP9 facilitates ECM degradation, enhancing vascular permeability and promoting tumor cell extravasation, while S100A8 fosters a pro-inflammatory microenvironment that sustains neutrophil survival and function." (PMID 40649918, 2025). "S100A8 and S100A9, both associated with CRC progression, were elevated, consistent with studies that examined their protein expression in tumour and matched distant normal tissues using IHC and WB39." (PMID 40348885, 2025). "Compared to cancer tissues, RNA expression level of S100A8/A9 was higher in adjacent non-tumor tissues." (PMID 40670349, 2025). "MMP9 facilitates ECM degradation, enhancing tumor cell migration, whereas fibronectin supports metastatic cell adhesion, and S100A8/S100A9 contribute to myeloid cell recruitment, generating a pro-inflammatory environment niche." (PMID 40649918, 2025). "This study provides the first comprehensive evaluation of S100A8 expression in both the tumor and immune compartments of endometrioid EC using TMAs." (PMID 41303754, 2025). "Inflammatory markers such as S100A8 and CRISP-3 showed differential expression based on lymph node status, reflecting tumor-associated inflammation and potential differences in lymphatic dissemination." (PMID 40710368, 2025). "An example is the study of tumor-associated macrophages (TAMs) in MCC, and the association of S100A8-expressing TAMs with resistance to anti-PD-L1 inhibitors (where PD-L1 stands for programmed death-ligand 1)." (PMID 40277767, 2025).